PRMT7 (protein arginine methyltransferase 7)
Description:
Arginine methyltransferase that can both catalyze the formation of omega-N monomethylarginine (MMA) and symmetrical dimethylarginine (sDMA), with a preference for the formation of MMA. Specifically mediates the symmetrical dimethylation of arginine residues in the small nuclear ribonucleoproteins Sm D1 (SNRPD1) and Sm D3 (SNRPD3); such methylation being required for the assembly and biogenesis of snRNP core particles. Specifically mediates the symmetric dimethylation of histone H4 'Arg-3' to form H4R3me2s. Plays a role in gene imprinting by being recruited by CTCFL at the H19 imprinted control region (ICR) and methylating histone H4 to form H4R3me2s, possibly leading to recruit DNA methyltransferases at these sites. May also play a role in embryonic stem cell (ESC) pluripotency. Also able to mediate the arginine methylation of histone H2A and myelin basic protein (MBP) in vitro; the relevance of such results is however unclear in vivo.
Synonyms: KIAA1933; FLJ10640; SBIDDS
Tractability: Small molecule: a high-quality ligand is known. PROTAC: ubiquitination databases record sites on it; its protein half-life has been measured; a small molecule that binds it is known.
Target class: Epigenetic regulator; Protein arginine methyltransferase; Writer; Protein methyltransferase
Chemical probes: DS-437, SGC3027 (high quality)
Gene: Protein-coding gene on chromosome 16 (68,310,916 to 68,360,852, forward strand). Ensembl gene ENSG00000132600.
Subcellular location: Cytoplasm, cytosol; Nucleus
Subcellular location (Human Protein Atlas): Nucleoplasm; Nucleoli fibrillar center
Pathways (Reactome):
Chromatin organization: RMTs methylate histone arginines
Gene Ontology:
Molecular function: histone binding; histone H4 methyltransferase activity; protein binding; protein-arginine omega-N monomethyltransferase activity; protein-arginine omega-N symmetric methyltransferase activity; ribonucleoprotein complex binding; S-adenosylmethionine-dependent methyltransferase activity; histone H4R3 methyltransferase activity; methyltransferase activity; protein-arginine N-methyltransferase activity
Biological process: spliceosomal snRNP assembly; genomic imprinting
Cellular component: cytosol; nucleoplasm; nucleus
Genetic constraint (gnomAD): Loss-of-function variants: 58 observed, 71.46 expected, observed/expected ratio (o/e) 0.81, 90% interval 0.66 to 1.01. The upper end of that interval is the gene's LOEUF score, 1.01, which puts it in group 4 of 6, group 1 being the genes least tolerant of losing a copy. Missense variants: 777 observed, 828.61 expected, observed/expected ratio (o/e) 0.94, 90% interval 0.88 to 1. Synonymous variants: 361 observed, 325.75 expected, observed/expected ratio (o/e) 1.11, 90% interval 1.02 to 1.21.
Homologues: Orthologues: chimpanzee PRMT7 (99% identical), macaque PRMT7 (95% identical), rabbit PRMT7 (88% identical), dog PRMT7 (87% identical), pig PRMT7 (86% identical), mouse Prmt7 (85% identical), guinea pig PRMT7 (84% identical), rat Prmt7 (84% identical), zebrafish prmt7 (62% identical), tropical clawed frog prmt7 (58% identical), Drosophila melanogaster Art7 (36% identical), Caenorhabditis elegans prmt-7 (31% identical). Paralogues in human: PRMT9 (23% identical), CARM1 (12% identical), PRMT3 (12% identical), PRMT2 (11% identical), PRMT8 (11% identical), PRMT1 (11% identical), PRMT6 (10% identical).
Diseases named in the same sentence as PRMT7 in open-access papers:
PRMT7 is named in the same sentence as 80 diseases in open-access papers, as found by Europe PMC text mining. Sharing a sentence is not in itself a finding about the gene and the disease. The quoted sentences say what the papers report.
breast carcinoma (16 papers, 2015 to 2026). "Two studies on breast cancer and lung cancer had associated increased PRMT7 levels to poor prognosis and survival." (PMID 38092752, 2023). "PRMT7 has been identified in several gene expression studies to be associated with increased metastasis and decreased survival in breast cancer patients." (PMID 25605249, 2015). "Depletion of PRMT7 in highly invasive breast cancer cells, MDA-MB-231 and BT549, caused a significant reduction in the ability of these cells to invade through an extracellular matrix-like barrier in vitro." (PMID 25605249, 2015). "Our assessment of MMP9 expression in invasive breast cancer cells showed that PRMT7 knockdown caused a significant decrease in MMP9 mRNA levels, secreted MMP9 protein amounts and decreased enzymatic activity." (PMID 25605249, 2015). "According to research conducted by Geng’s team, PRMT7 in breast cancer is associated with both epigenetic modifications in the methylation modification of its substrate and self-methylation processes that are closely linked to the metastasis of breast cancer." (PMID 41154773, 2025). "The progression of breast cancer is primarily linked to PRMT7." (PMID 41154773, 2025). "PRMT7 overexpression has been closely associated with breast cancer and leukemia." (PMID 36293180, 2022). "Prmt7 expression is also associated with the metastasis of breast cancer." (PMID 36013373, 2022). "In addition, since PRMT7 overexpression has been implicated in various cancers, including breast cancer and leukemia, PRMT7 is emerging as a potential target for cancer treatment." (PMID 36293180, 2022). "Thus further supporting the association of increased PRMT7 expression in aggressiveness of breast cancer cells." (PMID 25605249, 2015). "PRMT7 is increased in prostate, colorectal, and breast cancer cells, leading to aberrant alternative splicing and elevated hnRNPA1 arginine methylation." (PMID 41154773, 2025). "In cancer research, PRMT7 is of significant interest due to its varying expression across several cancers, including prostate cancer, breast cancer, melanoma, non-small-cell lung cancer (NSCLC), gastric cancer, T-ALL, liver cancer, and renal cell carcinoma." (PMID 40869229, 2025). "Relevant research has demonstrated that basal breast cancer cells overexpress PRMT7, which increases the production of MMP2 and MMP9 to encourage cancer cell invasion and metastasis." (PMID 41154773, 2025). "Several studies have confirmed that PRMT1, PRMT2, PRMT3, and PRMT7 are overexpressed in breast cancer." (PMID 35216622, 2022). "For example, high expression levels of Prmt7 are correlated with the proliferation and metastasis of breast cancer cells, lung cancer tissues, and clear cell renal cell carcinoma tissues." (PMID 36013373, 2022). "PRMT7 was reported to be highly expressed in breast carcinoma cells in which it inhibited E-cadherin expression, consequently mediating breast cancer metastasis." (PMID 34712331, 2021). "In breast carcinoma cells, increased PRMT7-mediated EMT and metastasis by losing E-cadherin expression due to altered histone methylation, specifically elevated H4R3me2s levels." (PMID 34440512, 2021). "Conversely, overexpression of PRMT7 in epithelial breast cancer cells promotes cell invasion by upregulating the MMP9 matrix metalloproteinase that is responsible for the degradation of the extracellular matrix enabling cancer cells to invade tissues." (PMID 34440512, 2021). "As low levels of MRPS23 result in breast cancer cell survival through regulating oxidative phosphorylation, PRMT7 overexpression inhibited oxidative phosphorylation and increased breast cancer cell invasion." (PMID 34440512, 2021). "Through a meta-analysis of gene expression in more than 120 breast tumors, PRMT7 was identified as a potential metastasis-promoting gene in breast cancer." (PMID 34712331, 2021).
breast carcinoma (continued). "The involvement of FAK in promoting breast cancer metastasis was also shown upon its interaction with Gpx1 or the protein arginine methyltransferase 7 (PRMT7)-dependent methylation of the scaffolding protein SH3 and multiple ankyrin repeat domains 2 (SHANK2)." (PMID 33562737, 2021). "Further mechanistic study revealed that PRMT7 promoted breast cancer cell invasion by regulating MMP9 (matrix metalloproteinase 9) which is a famous mediator of breast cancer metastasis." (PMID 34712331, 2021). "Accordingly, PRMT7 was also overexpressed in breast cancer tissues and invasive breast cancer cells." (PMID 34712331, 2021). "An assessment of the composite score distribution demonstrated that a significant proportion of breast cancer tissues (68%) and lymph node metastases (68%) had a strong expression (6+ composite score) of PRMT7." (PMID 25605249, 2015). "PRMT7 protein expression was significantly higher (~3 to 5-fold) in highly invasive breast cancer cells compared to MCF10A and MCF7 cells." (PMID 25605249, 2015). "In this study we have shown that PRMT7 plays a functional role in promoting breast cancer cell invasion." (PMID 25605249, 2015). "To determine if PRMT7 knockdown affects breast cancer cell invasion in vivo, we performed an experimental metastasis study." (PMID 25605249, 2015). "Taken together, these experiments demonstrate that PRMT7-regulated expression of MMP9 influences the invasive capabilities of breast cancer cells." (PMID 25605249, 2015). "Nevertheless our results have demonstrated that directly targeting and decreasing expression of PRMT7 causes reduced MMP9 expression, which specifically in breast cancer, is a therapeutically advantageous effect." (PMID 25605249, 2015). "This evidence supports our observation that PRMT7 is overexpressed in breast cancer, and more specifically invasive cancer cells." (PMID 25605249, 2015). "This identifies PRMT7 as a novel and potentially significant biomarker and therapeutic target for breast cancer." (PMID 25605249, 2015). "To assess the expression of PRMT7 in breast cancer tissues, we used four commercially available high-density tissue microarrays (TMA)." (PMID 25605249, 2015). "We have shown that specific knockdown of PRMT7 using RNA interference resulted in decreased breast cancer cell invasion in vitro and also metastasis in vivo." (PMID 25605249, 2015). "Data from these consortiums suggest that a significant proportion of breast cancers display increased PRMT7 gene expression." (PMID 25605249, 2015). "Overall, we have clearly established PRMT7 as a key mediator of breast cancer cell invasion and metastasis." (PMID 25605249, 2015). "The precise mechanism through which PRMT7 is acting to regulate MMP9 expression within breast cancer cells requires further elucidation." (PMID 25605249, 2015). "Our examination of PRMT7 protein expression in breast cancer cells has also potentially uncovered an additional unique feature of PRMT7, the potential existence of alternative species." (PMID 25605249, 2015). "Alternatively, ectopic overexpression of PRMT7 in weakly invasive breast cancer cells enhanced their ability to invade." (PMID 25605249, 2015). "This localization of PRMT7 is consistent with what we have observed for endogenous PRMT7 by immunofluorescence in breast cancer cells and also with previous observations." (PMID 25605249, 2015). "Altogether, these results are highly suggestive that PRMT7 plays a significant role in promoting breast cancer cell invasion, a necessary characteristic leading to metastasis." (PMID 25605249, 2015). "It has been suggested from previous unbiased studies and through mining online expression databases that PRMT7 gene expression is dysregulated in breast cancer." (PMID 25605249, 2015). "To examine the role of PRMT7 in cancer cell motility and invasion we used the highly invasive breast cancer cell lines, MDA-MB-231 and BT549." (PMID 25605249, 2015).
breast carcinoma (continued). "Due to the fact that PRMT7 is overexpressed in invasive breast cancer cells, we wanted to assess its importance in promoting cell invasiveness." (PMID 25605249, 2015). "We have demonstrated that reducing PRMT7 levels in invasive breast cancer cells using RNA interference significantly decreased cell invasion in vitro and metastasis in vivo." (PMID 25605249, 2015). "Here we have shown that PRMT7 protein expression is significantly increased in primary breast tumour tissues and breast cancer metastatic tissues." (PMID 25605249, 2015). "Here we report that PRMT7 expression is significantly upregulated in both primary breast tumour tissues and in breast cancer lymph node metastases." (PMID 25605249, 2015). "In summary, our results demonstrate a novel role for PRMT7 in the regulation of breast cancer cell invasion." (PMID 25605249, 2015). "Our assessment of PRMT7 expression in breast tumour tissues has demonstrated that PRMT7 protein expression is upregulated in primary breast tumour tissues and breast cancer metastases." (PMID 25605249, 2015). "We next examined the expression of PRMT7 in established human breast cancer cell lines in order to corroborate our observations in human breast tumour tissues and validate their use as an experimental model." (PMID 25605249, 2015). "Reduced expression of PRMT7 inhibited breast cancer cell invasion both in vitro and in vivo." (PMID 34712331, 2021). "PRMT7 automethylation itself also seems to play a role in breast cancer metastasis." (PMID 34440512, 2021). "Targeting PRMT7 expression or enzyme activity could be a therapeutic strategy for human breast cancer." (PMID 34712331, 2021). "In addition to breast cancer and lung cancer, it was recently found that PRMT7 expression was increased in clear cell renal cell carcinoma tissues as well." (PMID 34712331, 2021). "Automethylation of PRMT7 R531 was reported to play a role in breast cancer cell migration." (PMID 34440512, 2021). "PRMT7 upregulates expression of metalloproteinase-9 (MMP-9) in breast carcinoma cells but its role in macrophages is unknown." (PMID 28228757, 2017). "For example, our group has demonstrated that PRMT7 expression is significantly upregulated in both primary breast tumor tissues and in breast cancer lymph node metastases, identifying PRMT7 as a key player in promoting breast cancer metastatic potential through regulation of MMP9 expression." (PMID 28698590, 2017). "Indeed, PRMT7 is localized in a region known to have an aberrant copy number in metastatic breast cancers." (PMID 27556302, 2016). "The rescue observed here was only partial, suggesting that PRMT7 may also affect breast cancer cell invasion through additional mechanisms/ pathways." (PMID 25605249, 2015). "This study established a functional role for PRMT7 in cancer, specifically in breast cancer." (PMID 25605249, 2015). "Interestingly, two closely migrating bands are detected for PRMT7 in several breast cancer cell lines by Western blot." (PMID 25605249, 2015). "Our results demonstrate that upregulation of PRMT7 in breast cancer may have a significant role in promoting cell invasion through the regulation of MMP9." (PMID 25605249, 2015). "To determine the effects of PRMT7 on invasion (cell motility combined with their ability to penetrate through physical barriers), we assessed the ability of invasive breast cancer cells with PRMT7 knockdown to migrate through Transwell chamber membranes coated with Matrigel." (PMID 25605249, 2015). "To determine if PRMT7 could promote breast cancer cell invasion, we overexpressed PRMT7 in MCF7 cells." (PMID 25605249, 2015). "Moreover, depletion of PRMT7 in highly invasive breast cancer cells using RNA interference decreased their invasiveness and ability to metastasize, in vitro and in vivo respectively." (PMID 25605249, 2015).
breast carcinoma (continued). "The association of PRMT7 expression with primary breast tumours and metastatic breast cancer led us to investigate whether PRMT7 directly affects breast cancer cell invasion." (PMID 25605249, 2015). "Importantly, we significantly rescued invasion of aggressive breast cancer cells depleted of PRMT7 by the exogenous expression of MMP9." (PMID 25605249, 2015). "Here, we have shown that PRMT7 plays a direct role in promoting human breast cancer cell invasion." (PMID 25605249, 2015). "PRMT7 protein expression is also increased in highly invasive breast cancer cell lines." (PMID 25605249, 2015). "We assessed PRMT7 protein expression in breast cancer tissues by immunohistochemistry." (PMID 25605249, 2015). "Alternatively, overexpression of PRMT7 in a non-aggressive breast cancer cell line caused them to become more invasive." (PMID 25605249, 2015). "Furthermore, the subcellular localization of our PRMT7-GFP fusion protein is consistent with what we observed for endogenous PRMT7 in breast cancer cells." (PMID 25605249, 2015). "Moreover, two independent groups demonstrated that PRMT7 is overexpressed in breast carcinomas." (PMID 27556302, 2016). "Analysis of clinical data showed that PRMT7 expression is negatively correlated with CD8+ infiltration and survival in breast cancer patient cohorts." (PMID 41565695, 2026). "In a breast cancer cell line, MCF7, a PRMT7 inhibitor combined with doxorubicin had synergistic effects on cytotoxicity." (PMID 40869229, 2025). "PRMT7-mediated EMT metastasis is promoted by H4R3 histone methylation changes, which decrease E-cadherin expression in breast cancer cells." (PMID 41154773, 2025). "The allosteric regulation between PRMT7 and PRMT5 should be considered, especially in breast cancer, where the role of PRMT5 in cancer-initiating cells and disease progression has been well established." (PMID 34440512, 2021). "In breast cancer, colorectal cancer, and prostate cancer cells, PRMT4, PRMT5, and PRMT7 and their mediated hnRNPA1 methylation and splicing isomerism can effectively promote the growth of cancer cells." (PMID 34603017, 2021). "This evidence reveals that PRMT7 is capable of inducing MMP9 expression, representing a mechanism through which PRMT7 can promote breast cancer cell invasion." (PMID 25605249, 2015). "Overexpression of PRMT7 in MCF7 cells, a weakly invasive breast cancer cell line, is sufficient to enhance their invasive capability." (PMID 25605249, 2015). "To date, no genetic alterations have been identified for the PRMT7 gene, however it is located in a genomic region known to display high copy number abnormalities in breast cancer." (PMID 25605249, 2015). "We initially thoroughly validated a PRMT7 polyclonal antibody for use in this study and have shown that it specifically detects PRMT7 in Western blots of breast cancer cell lines with no other non-specific activity." (PMID 25605249, 2015). "Furthermore, an assessment of PRMT7 expression using the unbiased genome-wide databases, ‘The Cancer Genome Atlas’, ‘Oncomine’ and the ‘ABREN’ revealed that it is dysregulated in breast cancer." (PMID 25605249, 2015). "Furthermore, we show that PRMT7 induces the expression of matrix metalloproteinase 9 (MMP9), a well-known mediator of breast cancer metastasis." (PMID 25605249, 2015). "Consistent with these tissue expression analyses, we have shown that PRMT7 expression is significantly increased in a subset of established breast cancer cell lines compared to non-tumourigenic normal breast epithelial cells (MCF10A)." (PMID 25605249, 2015).
lung carcinoma (6 papers, 2021 to 2025). "PRMT7 has been identified to play vital roles in breast and lung cancer by regulating metastasis and EMT transition." (PMID 38092752, 2023). "Prmt7 overexpression promotes the malignant progression of nonsmall cell lung cancer cells and the growth of renal cell carcinoma." (PMID 36013373, 2022). "PRMT7 overexpression also promoted the invasion and colony formation in lung cancer, and the authors of this study found that PRMT7 interacted with mitochondria localized HSP70 family member HSPA5 and elongation factor 2 EEF2." (PMID 34440512, 2021). "An online database analysis indicated that lung cancer tissues exhibited higher PRMT7 expression than healthy tissues." (PMID 34712331, 2021). "Furthermore, the lung carcinoma datasets from cBioPortal showed that SOX9 mRNA levels did not correlate with PRMT7 mRNA levels." (PMID 41428171, 2025).